WDR31 (WD repeat domain 31)
Synonyms: FLJ35921
Tractability: No criterion of Open Targets' tractability assessment is met for any kind of drug.
Gene: Protein-coding gene on chromosome 9 (113,313,222 to 113,340,337, reverse strand). Ensembl gene ENSG00000148225.
Subcellular location (Human Protein Atlas): Cytosol; Nuclear bodies
Genetic constraint (gnomAD): Loss-of-function variants: 30 observed, 49 expected, observed/expected ratio (o/e) 0.61, 90% interval 0.46 to 0.83. The upper end of that interval is the gene's LOEUF score, 0.83, which puts it in group 3 of 6, group 1 being the genes least tolerant of losing a copy. Missense variants: 406 observed, 464.75 expected, observed/expected ratio (o/e) 0.87, 90% interval 0.81 to 0.95. Synonymous variants: 136 observed, 168.31 expected, observed/expected ratio (o/e) 0.81, 90% interval 0.7 to 0.93.
Homologues: Orthologues: chimpanzee WDR31 (99% identical), macaque WDR31 (96% identical), dog WDR31 (88% identical), pig WDR31 (86% identical), guinea pig WDR31 (85% identical), rabbit WDR31 (84% identical), mouse Wdr31 (83% identical), rat Wdr31 (73% identical), zebrafish wdr31 (50% identical), Caenorhabditis elegans wdr-31 (27% identical).
Diseases named in the same sentence as WDR31 in open-access papers:
WDR31 is named in the same sentence as 4 diseases in open-access papers, as found by Europe PMC text mining. Sharing a sentence is not in itself a finding about the gene and the disease. The quoted sentences say what the papers report.
ciliopathy (1 paper, 2023). A genetic disorder of the cellular cilia or the cilia anchoring structures, the basal bodies, or of ciliary function. "The exclusive cilia expression pattern of wdr-31 in C. elegans is similar to that of ciliary and ciliopathy genes like ARL-13/ALR13B, IFT, and BBS." (PMID 37208194, 2023). "The lack of an apparent cilia phenotype in C. elegans may be attributed to a functional redundancy for WDR-31 in cilia biogenesis, and functional redundancy is indeed a common phenomenon in ciliopathy-related genes." (PMID 37208194, 2023).
Crohn disease (1 paper, 2023). A gastrointestinal disorder characterized by chronic inflammation involving all layers of the intestinal wall, noncaseating granulomas affecting the intestinal wall and regional lymph nodes, and transmural fibrosis. "In summary, the stricturing and penetrating Crohn’s disease phenotype is characterized by distinct proteomic signatures, evidenced by elevated serum levels of WDR31, LRG1, and SAA1." (PMID 38069288, 2023).
WDR31 also shares sentences with these, for which no sentence is quoted: cancer (1 paper); endometrial carcinoma (1).